LINC01115 (long independently transcribed non-coding RNA 1115)
Gene: Long non-coding RNA gene on chromosome 2 (733,471 to 868,608, reverse strand). Ensembl gene ENSG00000237667.
Diseases named in the same sentence as LINC01115 in open-access papers:
LINC01115 is named in the same sentence as 1 disease in open-access papers, as found by Europe PMC text mining. Sharing a sentence is not in itself a finding about the gene and the disease. The quoted sentences say what the papers report.
schizophrenia (1 paper, 2019). A major psychotic disorder characterized by abnormalities in the perception or expression of reality. "In addition, schizophrenia-specific chromatin modifications in neurons were particularly prominent for non-coding RNA genes, including an uncharacterized LINC01115 gene and recently identified BNRNA_052780." (PMID 31624234, 2019).